INS (insulin)
Diseases named in the same sentence as INS in open-access papers (continued):
Sharing a sentence is not in itself a finding about the gene and the disease.
diabetes (continued). "It is believed that the release of insulin in the first phase is particularly relevant to glucose tolerance, because abnormalities in this route may signal the onset of diabetes changes." (PMID 35462799, 2022). "In addition, the continual self-care required in the treatment of diabetes (blood sugar measurements, multiple doses of insulin, diet, exercise, etc.), is much harder to ensure in patients affected by concomitant depression." (PMID 35782445, 2022). "Besides antidiabetes drugs and insulin, various medications and supplies are needed to manage diabetes and confounding diseases." (PMID 36177396, 2022). "The vast majority of diabetes is divided into two categories, type 1 diabetes: an absolute lack of insulin secretion, and type 2 diabetes: the cause is a combination of resistance to insulin action and an inadequate compensatory insulin secretory response." (PMID 35656112, 2022). "In addition, TMAO has been linked to obstruct the hepatic insulin signaling pathway, and the correlations between TMAO and diabetes risk appeared to be more reliable than those for cardiovascular risk." (PMID 35886563, 2022). "A study speculated sulphonylureas may play a role in CRC carcinogenesis impairing the physiological insulin secretion among diabetes participants." (PMID 36407320, 2022). "The direct injection of insulin (INS) is currently the only effective treatment for diabetes." (PMID 36139080, 2022). "Among 1,013 DFI episodes in 586 patients (78% males; median age 67 years) occurring during the study period, 882 (87%) had DFO, 388 (38%) had a disorder associated with enhanced immunosuppression (beyond their diabetes mellitus), and 753 (74%) were insulin-treated diabetes cases." (PMID 36034588, 2022). "Increased consumption may be beneficial for older adults with diabetes due to the combined effect of dairy on both insulin sensitivity and lean body mass." (PMID 35831938, 2022). "Diabetes comprises mainly two types, Type 1(insulin dependent) and Type 2 (non-insulin dependent)." (PMID 35947580, 2022). "Mice were either fed with a high-fat diet to induce obesity and T2D, had a genetic defect in insulin signaling causing systemic insulin resistance but not full-blown diabetes (IR/IRS-1+/mice), or were treated with streptozotocin to induce T1D." (PMID 36012137, 2022). "Whilst numerous drugs, including various formulations of the beta-cell hormone insulin, are available to combat diabetes mellitus, adequate control of plasma glucose and the long-term cardiovascular and neuropsychiatric complications of the disorder remain a serious problem." (PMID 35207609, 2022). "In a previous study, the number of patients with diabetes using insulin in China was ~9 million." (PMID 36568796, 2022). "Furthermore, a mother with diabetes was urged to go back to the maternity ward because it was time for her to take her insulin." (PMID 35067210, 2022). "Evidences has shown that insulin therapy improves diabetes symptoms and delay of insulin initiation may lead to significant number of diabetes related complications." (PMID 35617250, 2022). "Those with diabetes and those reporting taking insulin may exhibit different patterns of misreporting compared with other population groups." (PMID 36014790, 2022). "Additionally, Beining encouraged the Federal Minister of Labor to contact the Insuline Committee, a panel of diabetes specialists set up in 1948 to control and improve standards for the application of insulin." (PMID 35166855, 2022). "The hypothesis that C albicans can disrupt insulin secretion, thus leading to diabetes, has been confirmed." (PMID 36397429, 2022). "The comprehensive phenotyping in the GDS, using gold-standard methodology, demonstrated large interindividual differences in people within 12 months of their diagnosis of diabetes regarding insulin sensitivity, beta cell function, islet-directed autoantibodies, blood lipids and BP." (PMID 34981134, 2022).
diabetes (continued). "Diabetes mellitus, characterized by high glucose levels is a chronic metabolic disorder with several different types of causes, mainly resistance to insulin, lack of insulin, and defects in the gene of the β-cells of the pancreas." (PMID 36557829, 2022). "In the case of diabetes mellitus, albumin synthesis relies on adequate insulin reserves." (PMID 36344933, 2022). "Factors that may link obesity and diabetes with thyroid proliferative disorders include elevated circulating levels of insulin, increased body fat, high blood sugars, and exogenous insulin use." (PMID 35158824, 2022). "Hyperglycemia caused by a deficiency in insulin production by the β-cells of the pancreas is known as Type 1 diabetes mellitus (T1DM) and due to insufficiency of insulin production in the face of insulin resistance or β-cells dysfunction is Type 2 diabetes mellitus (T2DM)." (PMID 36091798, 2022). "Diabetes, which is a chronic disease that occurs either when the pancreas does not produce enough insulin or when the body cannot effectively use the insulin it produces, affected 422 million of people in 2014, and its prevalence still increases, especially in low- and middle-income countries." (PMID 35893405, 2022). "In addition, ATP6AP2 is critical for regulating the stored insulin pool and a balanced regulation of granule turnover is key to maintaining beta cell function and diabetes prevention." (PMID 35885938, 2022). "Transplantations as treatments for T1DM are generally only considered in patients who exhibit a history of hard to control diabetes, defined as ≥1 episode of severe hypoglycemia per year, frequent and severe metabolic or microvascular complications, and problems with exogenous insulin therapy." (PMID 35324794, 2022). "Regarding the role of diabetes mellitus in determining ischemic lesions and the occurrence of NR, it has been observed that both insulin- and non-insulin-dependent diabetes mellitus are associated with an increased risk of ischemic cardiovascular disease." (PMID 35453980, 2022). "Here, we show that modulating PM flipping of Stx2 from inside (inhibitory) to the exterior (relief of inhibition) of the β-cell assists the precise tuning of insulin secretion, and this flipping efficiency can be used to alleviate the impaired insulin secretion in diabetes." (PMID 36316316, 2022). "Mothers who had insulin-treated diabetes had the highest risk of having LGA offspring regardless of BMI." (PMID 36329895, 2022). "Mitochondrial dysfunction may induce diabetes by affecting insulin secretion of islet β-cells and aggravating insulin resistance." (PMID 35056765, 2022). "In addition, these acids provide multiple benefits in diabetes, particularly by stimulating glucagon-like peptide 1 and insulin secretion." (PMID 36672580, 2022). "In addition, pancreatic β cells overexpress IL-15 and Il-5α double transgenic mice, which appear similar to human insulin antibodies, which induce β cell destruction, while inhibiting IL-15 and IL-5α that can reverse the progression of diabetes." (PMID 35242879, 2022). "Notably, oxidative stress is linked with the activation of protein kinase C (PKC), which is normally consistent with impaired insulin signaling and tissue damage in experimental models of diabetes." (PMID 35899107, 2022). "It was found that dietary supplementation with chromium decreased insulin concentration in the blood of healthy rats and improved insulin sensitivity, and decreased glycosylated hemoglobin (HbA1c) and glucose levels in animals with induced diabetes, insulin resistance, or metabolic syndrome." (PMID 36290631, 2022). "In this study, the PDR patients treated with insulin had a longer course of diabetes." (PMID 35937830, 2022).
diabetes (continued). "Insulin biosimilar showed comparable characteristics with the reference drug in terms of efficacy, safety, and immunogenicity through comprehensive and specific conventional meta-analysis, even in the subgroup analysis of the different types of diabetes and different duration of insulin." (PMID 35123455, 2022). "A study in mongrel dogs with diabetes showed prolongation of the QT interval and a diminished IKs density, which could be prevented by insulin." (PMID 35990966, 2022). "Others found that miR-92a with diabetes could inhibit apoptosis induced by a high-glucose environment and could increase insulin secretion by targeting Kruppel Like Factor 2 (KLF2)." (PMID 36874371, 2022). "One of the most effective treatments for diabetes is to design a glucose-regulated insulin (INS) delivery system that could adjust the INS release time and rate to reduce diabetes-related complications." (PMID 36246353, 2022). "Those having eGDR <8 had higher age, longer duration of diabetes, high WC, insulin dose, and BMI." (PMID 35703516, 2022). "In NOD mice, pharmacological inhibition of DHPS by administration of N1-guanyl-1,7-diaminoheptane (GC7) during the prediabetic stage resulted in improved glucose tolerance, greater insulin secretion, decreased immune infiltration of islets, and a delay of diabetes onset." (PMID 35448531, 2022). "37% of the patients presented with peripheral insulin resistance (pre-existing diabetes treated by oral antidiabetic drugs or insulin or elevated HbA1c), 43% had a hyperlipidemia (high serum level of cholesterol, HDL, LDL or triglyceride) and 47% were diagnosed with steatosis or atherosclerosis." (PMID 35784287, 2022). "Diabetes mellitus is a deadly metabolic disease which results from excessive amounts of sugar in the blood of the patient, either due to insufficient production of insulin or inability of the cells to use the produced insulin properly." (PMID 36615320, 2022). "Moreover, hypoglycemia is observed with AD patients in early stage and diabetes and impaired insulin signaling further worsen the pathogenesis of AD." (PMID 36148311, 2022). "The purpose of this study was to determine whether 2-O-M functions as an activator of the insulin signaling pathway, regulating glucose hemostasis through the InsR and exerting a glucose-lowering effect in an animal model of diabetes." (PMID 35502441, 2022). "Insulin is typically used to control hyperglycemia in patients with diabetes." (PMID 36482537, 2022). "About a third (35%) were on insulin therapy, while 75.4% had been exposed to diabetes education." (PMID 37575630, 2022). "In addition, chronic ABA treatment, starting after diabetes induction, improves the glycemia profile in the presence of residual endogenous insulin, and improves the hypoglycemic action of exogenous insulin." (PMID 35736456, 2022). "Since the Insulin Committee had been taken over by the German Diabetes Society (Deutsche Diabetes Gesellschaft, DDG) as the preeminent body of diabetes specialists, the request was handed over to the chair of the society’s Panel for Social Medicine, headed by Günther Kurow (1921–2001)." (PMID 35166855, 2022). "Special attention was paid on application of the state-of-the-art CRISPR/Cas9 technology, based on targeted epigenome editing with the purpose of changing the differentiation state of different cell types, making them insulin-producing with ability to attenuate diabetes." (PMID 36246880, 2022). "About 25% of diabetes patients require administration of insulin." (PMID 35350789, 2022). "Sedentary behavior, independent of weight status, can decrease insulin sensitivity and predispose to diabetes." (PMID 36040204, 2022). "Therefore, in this review, we gathered up-to-date knowledge on skeletal muscle uncoupling proteins and their effect on insulin sensitivity in mouse models of obesity and diabetes." (PMID 35323702, 2022).
diabetes (continued). "Standard diabetes therapy using adjusted subcutaneous insulin injections (sliding-scale insulin) combined with insufficient glucose monitoring is another issue and a potential risk factor for hypoglycemia, aggravated by the frequent shortage of nursing staff in hospitals." (PMID 35526139, 2022). "Increased IL-1 levels in GCF were observed in patients with insulin depended diabetes and hyperlipidemia, thus, a vicious cycle may develop." (PMID 36361416, 2022). "Therefore, reducing glucose uptake and ER stress, increasing glucose utilization, and facilitating insulin signal transduction are essential for improving and treating diabetes." (PMID 38647883, 2022). "Indeed, alpha-to-beta-cell lineage conversion is enhanced in GCGR KO mice, and more recently, human alpha-cells were shown to be capable of reprogramming into glucose-sensitive insulin-secreting cells to help ameliorate diabetes in mice." (PMID 36005280, 2022). "Some of them are referred to in the following section, such as the amyloid protein with Alzheimer’s disease, α1-antitrypsin with α1-antitrypsin deficiency (AATD), β-glucocerebrosidase (β-GCases) with Gaucher’s disease, the chloride channel and ENaC with cystic fibrosis, or insulin with diabetes." (PMID 35628387, 2022). "Unlike typical type 2 diabetes mellitus (T2DM), diabetes in PDA patients manifests as hyperglycemia with normal or relatively lower insulin levels caused by the removal of normal pancreatic tissue." (PMID 36211828, 2022). "At present, diabetes is treated with oral hypoglycemic drugs and insulin injections." (PMID 35056765, 2022). "The medical history included HIV infection and insulin-treated diabetes." (PMID 35295985, 2022). "Previous studies reported that physical activity mediated the acute insulin response through improvement in insulin resistance, and in a participant with insulin resistance and type 2 diabetes mellitus, physical activity decreased insulin secretion and increased insulin clearance." (PMID 36585722, 2022). "Type 2 diabetes mellitus (T2DM) represents a scenario of resistance to insulin hormone, augmented advanced glycation end products (AGEs), a pro-inflammatory phenotype, and the presence of oxidative stress (OS), leading to micro- and macrovascular complications." (PMID 36362238, 2022). "To conclude, long-term consumption of CM by patients with diabetes could be a useful adjuvant therapy alongside classical medications, especially in lowering the required insulin dose and HbA1c." (PMID 35334901, 2022). "Thus, recent studies demonstrated that a longer duration of diabetes involves complex therapy, including insulin." (PMID 36611296, 2022). "We observed that patients with discordant ASA class had a significantly higher proportion of comorbid clinical conditions (raised creatinine, diabetes mellitus on insulin, history of congestive heart failure, cerebrovascular accident, ischemic heart disease and smoking)." (PMID 35501421, 2022). "MUFAs also have beneficial effects on insulin sensitivity and type 2 diabetes mellitus." (PMID 36035400, 2022). "Although there is a large body of suggestions demonstrating the ability of camel milk to balance glucose, increase insulin production, reduce insulin resistance, and improve lipid properties, as well as powerful anti-diabetes capabilities in clinical trials, in vitro and in vivo therapies." (PMID 35898909, 2022). "Type 2 diabetes is the most common type of diabetes; it is a metabolic disorder, with multiple etiologies, characterized by carbohydrate, lipid, and protein metabolic disorders that include defects in insulin secretion, with a major contribution to insulin resistance." (PMID 36297817, 2022). "A pragmatic, unblinded, 6-month randomized controlled trial sought to recruit 146 patients with ≥1 diagnosis of heart failure (HF), uncontrolled hypertension (HT), and insulin-requiring diabetes mellitus (DM) from outpatient specialty settings in Toronto, Ontario, Canada." (PMID 35080502, 2022).
diabetes (continued). "A long history of diabetes duration (>10 years) and the use of oral antidiabetics with or without insulin application were reported as predisposing patients' characteristics." (PMID 35402477, 2022). "Collectively, these data provide novel information regarding the metabolic pathways that correlate with insulin sensitivity levels in skeletal muscle and may represent early events for developing insulin resistance, pre-diabetes, and type 2 diabetes." (PMID 36876056, 2022). "The more common type 2 diabetes mellitus (T2DM) results from resistance to insulin action and may be present for many years before detection." (PMID 35204128, 2022). "Although obesity is known to be linked to type 2 diabetes in humans, in dogs, diabetes is generally due to the lack of insulin-producing pancreatic β cells." (PMID 36262532, 2022). "In diabetes, lipolysis ensues due to the diminished insulin level and its action." (PMID 35186807, 2022). "Given these advantages, the link between COVID-19 and diabetes and the antiviral, antihyperglycemic, insulin-enhancing, and anti-inflammatory properties of vanadium compounds may be considered adjuncts to COVID-19 treatment." (PMID 35252118, 2022). "Barriers to optimal diabetes regulation in this life phase include steeply reduced insulin requirements immediately after delivery, adherence to a diet with sufficient carbohydrate intake and frequent blood glucose monitoring while coping with the demands of motherhood." (PMID 36432552, 2022). "A final possible explanation for longer diabetes-free survival among LKDs with obesity in the first decade post-donation may be rooted in altered insulin and glucose metabolism following donor nephrectomy." (PMID 36399462, 2022). "The interconnection between diabetes mellitus and kidney stones is mainly due to the effect of insulin resistance on urinary pH and and the transport of ammonia and calcium in the kidney, which affects the production and transport of ammonium, causing a decrease in urinary pH." (PMID 35844866, 2022). "Consequently, some people with diabetes are turning to social media crowdfunding as an attempt to relieve financial stress and obtain insulin." (PMID 35436214, 2022). "In addition, fasting insulin levels, and OGTT insulin at 0.5 h, 1 h, 1.5 h, and 2 h were significantly lower in the Diabetes-β-Cell-Failure group (P < 0.001)." (PMID 36211668, 2022). "Adiponectin regulates insulin sensitivity, increases fat metabolism, regulates glucose tolerance, and modifies homeostasis in order to protect people from diabetes, which makes it the strongest biomarker for type 2 diabetes mellitus." (PMID 35664415, 2022). "Insulin resistance may result in full-blown diabetes when pancreatic beta-cells become too damaged and incapable of supplying enough insulin." (PMID 35276982, 2022). "Additionally, diabetes patients stay on the lookout for more ways to paste the insulin pump on their body." (PMID 36141360, 2022). "Therefore, it would be beneficial to discover new small molecular natural compounds that can act as insulin sensitizers for use as compliments to insulin for patients with diabetes." (PMID 35502441, 2022). "In addition, GLUT2 participates in the glucagon and insulin signaling pathways, which are closely related to the occurrence of diabetes." (PMID 35283765, 2022). "One could compare this phenomenon with the burnout of beta cells of Langerhans island cells in the pancreas of diabetes patients where insulin resistance increasingly leads to the dysfunction or dying of beta cells." (PMID 36430527, 2022). "Patients diagnosed with diabetes in the context of acute COVID-19 were more likely to be prescribed insulin with 91 days of diagnosis (52/420, 12%, compared with 11/166, 7%, for controls) but there was no clear evidence of an increase in type 1 DM at any stage of the illness." (PMID 35853019, 2022).